ASXL2 (ASXL transcriptional regulator 2)
Description:
Putative Polycomb group (PcG) protein. PcG proteins act by forming multiprotein complexes, which are required to maintain the transcriptionally repressive state of homeotic genes throughout development. PcG proteins are not required to initiate repression, but to maintain it during later stages of development. They probably act via methylation of histones, rendering chromatin heritably changed in its expressibility (By similarity). Involved in transcriptional regulation mediated by ligand-bound nuclear hormone receptors, such as peroxisome proliferator-activated receptor gamma (PPARG). Acts as coactivator for PPARG and enhances its adipocyte differentiation-inducing activity; the function seems to involve differential recruitment of acetylated and methylated histone H3. Non-catalytic component of the PR-DUB complex, a complex that specifically mediates deubiquitination of histone H2A monoubiquitinated at 'Lys-119' (H2AK119ub1). The PR-DUB complex is an epigenetic regulator of gene expression and acts as a transcriptional coactivator, affecting genes involved in development, cell communication, signaling, cell proliferation and cell viability. ASXL1, ASXL2 and ASXL3 function redundantly in the PR-DUB complex (By similarity). The ASXL proteins are essential for chromatin recruitment and transcriptional activation of associated genes (By similarity). ASXL1 and ASXL2 are important for BAP1 protein stability.
Synonyms: ASXH2; KIAA1685; FLJ10898; SHAPNS
Tractability: PROTAC: ubiquitination databases record sites on it; its protein half-life has been measured.
Gene: Protein-coding gene on chromosome 2 (25,733,753 to 25,878,487, reverse strand). Ensembl gene ENSG00000143970.
Subcellular location: Nucleus
Subcellular location (Human Protein Atlas): Nucleoplasm
Pathways (Reactome):
Metabolism of proteins: UCH proteinases
Gene Ontology:
Molecular function: peroxisome proliferator activated receptor binding; protein binding; chromatin binding; DNA binding
Biological process: positive regulation of fat cell differentiation; positive regulation of peroxisome proliferator activated receptor signaling pathway; positive regulation of transcription by RNA polymerase II; animal organ morphogenesis; regulation of DNA-templated transcription
Cellular component: nucleoplasm; PR-DUB complex; nucleus
Genetic constraint (gnomAD): Loss-of-function variants: 18 observed, 111.65 expected, observed/expected ratio (o/e) 0.16, 90% interval 0.11 to 0.24. The upper end of that interval is the gene's LOEUF score, 0.24, which puts it in group 1 of 6, group 1 being the genes least tolerant of losing a copy. Missense variants: 1,497 observed, 1,738.4 expected, observed/expected ratio (o/e) 0.86, 90% interval 0.82 to 0.9. Synonymous variants: 629 observed, 649.96 expected, observed/expected ratio (o/e) 0.97, 90% interval 0.91 to 1.03.
Gene-disease validity (ClinGen):
ClinGen rates the evidence that ASXL2 causes each of these diseases.
syndromic intellectual disability (autosomal dominant): Definitive. A intellectual disability that is part of a larger syndrome.
Homologues: Orthologues: chimpanzee ASXL2 (99% identical), macaque ASXL2 (97% identical), dog ASXL2 (87% identical), pig ASXL2 (86% identical), guinea pig ASXL2 (85% identical), rabbit ASXL2 (81% identical), rat Asxl2 (80% identical), mouse Asxl2 (78% identical), tropical clawed frog asxl2 (48% identical), zebrafish asxl2 (37% identical), Drosophila melanogaster Asx (17% identical). Paralogues in human: ASXL3 (31% identical), ASXL1 (29% identical).
Diseases named in the same sentence as ASXL2 in open-access papers:
ASXL2 is named in the same sentence as 49 diseases in open-access papers, as found by Europe PMC text mining. Sharing a sentence is not in itself a finding about the gene and the disease. The quoted sentences say what the papers report.
leukemia (7 papers, 2017 to 2025). A malignant (clonal) hematologic disorder, involving hematopoietic stem cells and characterized by the presence of primitive or atypical myeloid or lymphoid cells in the bone marrow and the blood. "In particular, considering the frequent mutations of ASXL1 in various types of leukemia, the synergistic role of ASXL2 and PRC2 complex in leukemia development and hematopoiesis has been explored." (PMID 38791157, 2024). "Expression of WT ASXL2 cDNA or cDNA constructs bearing leukemia-associated mutant forms of ASXL2 revealed reduced stability of mutant ASXL2 relative to WT ASXL2, with greater loss of mutant ASXL2 following cycloheximide exposure." (PMID 28516957, 2017). "Interestingly, this identified a number of genes known to promote leukemogenesis (either alone or in the context of AML1-ETO leukemia) as differentially expressed by ASXL2 loss." (PMID 28516957, 2017). "Overall, these data highlight Asxl2 as critical for normal haematopoiesis as well as a novel haploinsufficient tumour suppressor in leukemia." (PMID 28516957, 2017). "Previous researches indicated that ASXL2 promotes cancer cell proliferation and invasion in colorectal cancer and breast cancer, while ASXL2 is found to be essential for hematopoiesis and as a tumor suppressor in leukemia." (PMID 34692512, 2021). "Given the alterations of enhancers in human AML1-ETO cells with ASXL2 loss, we next examined the chromatin state of AE9a leukemias with or without Asxl2 expression by transposase-accessible chromatin sequencing (ATAC-Seq)." (PMID 28516957, 2017). "The relationship between ASXL3 and tumor development is unclear, as it is rarely mutated and not as closely associated with leukemia as ASXL1 and ASXL2." (PMID 38791157, 2024).
myeloid malignancies (5 papers, 2017 to 2025). "A mechanistic explanation for the mutual exclusivity of ASXL1 mutations with ASXL2 mutations in myeloid malignancies remains to be clarified." (PMID 36068610, 2022). "While ASXL2 is identified to be essential for hematopoiesis and loss of Asxl2 in mice can lead to myeloid malignancies." (PMID 34692512, 2021). "In the current study, utilizing a murine model of Asxl2 loss, we sought to explore the role of ASXL2 in normal and malignant haematopoiesis, and to identify the mechanisms by which Asxl2 loss contribute to myeloid malignancies." (PMID 28593990, 2017). "Collectively, our results demonstrate that ASXL2 plays an important role in normal haematopoiesis and Asxl2 loss in mice leads to myeloid malignancies." (PMID 28593990, 2017). "Future work is warranted to decipher this critical question and unveil the roles of ASXL1 and ASXL2 mutations in the pathogenesis of myeloid malignancies." (PMID 28593990, 2017). "The Asxl2 knockout mice present an ideal model for unveiling the mechanisms underlying the Asxl2-loss-mediated multiple-step pathogenesis of myeloid malignancies and for testing novel therapeutic agents for myeloid malignant patients with ASXL2 mutations." (PMID 28593990, 2017). "Transplantation of bone marrow (BM) cells from Asxl2−/− or Asxl2+/− mice led to a leukaemic transformation in the lethally irradiated recipients, indicating a cell-autonomous effect of Asxl2 loss on the pathogenesis of myeloid malignancies." (PMID 28593990, 2017). "In addition to their roles in myeloid malignancies, deletion studies in mice have shown that both Asxl1 and Asxl2 regulate hematopoiesis, whereas the role of Asxl3 in hematopoiesis remains unexplored." (PMID 38791157, 2024). "Finally, what is the mechanistic explanation for the mutual exclusivity of ASXL1 mutations with ASXL2 mutations in myeloid malignancies, and why are ASXL1 mutations more prevalent in myeloid malignancies compared with ASXL2 mutations?" (PMID 36068610, 2022). "Importantly, both Asxl2+/− and Asxl2−/− BM recipient mice had a shortened lifespan due to the development of myeloid malignancies." (PMID 28593990, 2017). "However, the roles of ASXL2 in normal haematopoiesis and the pathogenesis of myeloid malignancies remain unknown." (PMID 28593990, 2017). "Myeloid Malignancy-Related Gene Mutation Screening: A panel of 67 genes associated with the diagnosis, treatment, prognosis, and recurrence of myeloid malignancies (including KIT, SRSF2, TET2, and ASXL2) was analyzed, with no relevant mutations identified." (PMID 40071101, 2025).
acute myeloid leukemia (4 papers, 2015 to 2019). Acute myeloid leukemia (AML) is a group of neoplasms arising from precursor cells committed to the myeloid cell-line differentiation. "This gene plays a significant role in neurodevelopment, cardiac function, adipogenesis, and osteoclastogenesis; the latest studies have shown that reproductive mutation gene ASXL2 in the maintenance of normal hematopoietic stem cell function of Acute Myeloid Leukemia (AML) has antitumor effect." (PMID 31888692, 2019).
myeloid leukemia (4 papers, 2017 to 2022). A clonal proliferation of myeloid cells and their precursors in the bone marrow, peripheral blood, and spleen. "ASXL2 is an epigenetic regulator associated with various tumors including colorectal cancer, breast cancer, and myeloid leukemia." (PMID 34692512, 2021). "Recipients transplanted with Asxl2−/− and Asxl2+/− BM cells have shortened lifespan due to the development of MDS-like disease or myeloid leukaemia." (PMID 28593990, 2017). "Collectively, these data indicate that a fraction of recipients transplanted with Asxl2+/− and Asxl2−/− BM cells developed myeloid leukaemia." (PMID 28593990, 2017). "Genes dysregulated by ASXL2 loss largely overlapped with those of RUNX1 and AML1-ETO and were associated with alterations in a number of genes previously shown to promote myeloid leukemias." (PMID 28516957, 2017).
Shashi-Pena syndrome (3 papers, 2017 to 2022). "Other important differential diagnosis includes Shashi-Pena syndrome (associated with a mutation in ASXL2), trisomies, Fragile X syndrome, lysosomal storage disorders, and all intellectual developmental disorders (autosomal dominant, autosomal recessive, and X-linked)." (PMID 36699804, 2022). "More recently, germline pathogenic variants in ASXL2 (reported in 2016) and ASXL3 (reported in 2013) were identified as the causes for Shashi-Pena syndrome (SHAPNS; MIM# 617190]) and Bainbridge-Ropers syndrome (BRS; MIM# 615485), respectively." (PMID 35361921, 2022).
anaemia (2 papers, 2017). "Necropsies of the moribund/deceased mice revealed that a fraction of Asxl2+/− and Asxl2−/− BM recipients had splenomegaly, severe anemia, decreased platelet counts and significantly higher percentages (>20%) of cKit+ cells in the BM." (PMID 28593990, 2017). "Mx1-cre Aml1-Eto Asxl2fl/WT mice expressing NRASG12D developed worsened anaemia and thrombocytopenia as well as greater circulating GFP/c-Kit double-positive cells and hastened death compared with counterpart Mx1-cre Aml1-Eto Asxl2 WT mice expressing NRASG12D." (PMID 28516957, 2017).
Bainbridge-Ropers syndromes (2 papers, 2022). "The ASXL gene family also includes ASXL2 and ASXL3, and variants in these genes are implicated in Shashi-Pena and Bainbridge-Ropers syndromes, respectively." (PMID 35361921, 2022). "Indeed, germ-line de novo truncating variants in human ASXL1, ASXL2, and ASXL3 cause the congenital and developmental disorders Bohring-Opitz, Shashi-Pena, and Bainbridge-Ropers syndromes, respectively, and somatic mutations of ASXL1, ASXL2, and ASXL3 occur in solid and hematologic malignancies." (PMID 36068610, 2022).
breast carcinoma (2 papers, 2021 to 2023). "In breast cancer, ASXL2 is demonstrated to promote tumor proliferation through linking ERalpha to histone methylation." (PMID 34692512, 2021).
colorectal cancer (2 papers, 2020 to 2021). A primary or metastatic malignant neoplasm that affects the colon or rectum. "An increasing number of studies have suggested that ASXL2 is an invasion-driver gene and overexpression of ASXL2 is correlated with prognosis in colorectal cancer." (PMID 34692512, 2021).
lipodystrophy (2 papers, 2020 to 2025). A congenital or acquired disorder characterized by abnormal loss or redistribution of the adipose tissue in the body. "Prior studies have shown that ASXL2 regulates lipid homeostasis; notably, ASXL2‐deficient mice develop lipodystrophy due to reduced PPARγ activity." (PMID 40300851, 2025). "Similarly, ASXL2 deficiency in mice model (ASXL2−/−) was directed towards insulin resistance, osteopetrosis, and lipodystrophy." (PMID 32605309, 2020).
melanoma (2 papers, 2018 to 2021). A malignant, usually aggressive tumor composed of atypical, neoplastic melanocytes. "We noted recurring missense mutations relevant to the ‘NEF’ loop in cBioPortal: Glu330 in ASXL2 is mutated in breast, bladder, and urothelial tumours; His315 in ASXL1 in colon, colorectal, lung cancer, and melanoma patient samples." (PMID 30258054, 2018).
myelodysplastic syndrome (2 papers, 2012 to 2017). A clonal hematopoietic disorder characterized by dysplasia and ineffective hematopoiesis in one or more of the hematopoietic cell lines. "We showed that Asxl2 loss led to a myelodysplastic syndrome (MDS)-like disease in mice as evidenced by pancytopenia, dysplastic features of myeloid cells and skewed differentiation towards myeloid lineages." (PMID 28593990, 2017). "Here we show that deletion of Asxl2 in mice leads to the development of myelodysplastic syndrome (MDS)-like disease." (PMID 28593990, 2017). "Mutations in ASXL2 and ASXL3 have not been found in myeloid diseases so far, but ASXL2-MYST3 and EPC1-ASXL2 fusions have been identified in myelodysplastic syndrome and T-cell acute leukemia, respectively." (PMID 22436456, 2012).
Splenomegaly (2 papers, 2017). Abnormal increased size of the spleen. "Of note, longitudinal evaluation of recipient mice transplanted with Mx1-cre Asxl2fl/fl mice up to 52 weeks failed to reveal any Asxl2-deficient mice to have developed increased white blood counts, splenomegaly or expansion of HSPCs." (PMID 28516957, 2017).
Bohring-Opitz syndrome (1 paper, 2017). "Similarly, heterozygous germline truncation of ASXL1 is the underlying cause of Bohring-Opitz syndrome, and related but distinct neurodevelopmental anomalies are associated with heterozygous germline truncation of ASXL2." (PMID 29037253, 2017).
Cachexia (1 paper, 2017). Severe weight loss, wasting of muscle, loss of appetite, and general debility related to a chronic disease. "These Asxl2+/− and Asxl2−/− BM recipient mice exhibited weight loss, pale foot pads and lack of activity, indicative of cachexia symptoms." (PMID 28593990, 2017).
coloboma (1 paper, 2009). An abnormality in which a part of a structure in one or both eyes is missing. "A role for Asxl2 in the eye has been previously speculated because a balanced reciprocal translocation between human ASXL2 and the Gt4-2 locus was discovered in a patient with bilateral colobomas in the retina and iris." (PMID 19270745, 2009).
intellectual disabilities (1 paper, 2020). "Among them is the ASXL transcriptional regulator 2 (ASXL2) gene, in which de novo germline truncation in ASXL2 variants have been associated with various clinical features of intellectual disabilities, macrocephaly, and dysmorphism." (PMID 32605309, 2020).
Kabuki syndrome (1 paper, 2025). Kabuki syndrome (KS) is a multiple congenital anomaly syndrome characterized by typical facial features, skeletal anomalies, mild to moderate intellectual disability and postnatal growth deficiency. "Similarly, there is a close resemblance between the DNAm signatures associated with pathogenic variants in ASXL2 and ASXL1 causing Shashi-Pena and Bohring-Optiz syndromes respectively, and between KDM6A and KMT2D variants causing Kabuki syndrome." (PMID 39843918, 2025).
malignant mesothelioma (1 paper, 2018). A malignant neoplasm of the pleura or peritoneum, arising from mesothelial cells. "Since we found that BAP1 activity is tightly regulated by UBE2Es-mediated ASXL2 monoubiquitination, we analyzed protein expression of these proteins in malignant mesothelioma, a cancer characterized by a high frequency of BAP1 mutations." (PMID 30349006, 2018). "We studied BAP1, ASXL2, and UBE2Es expression in 10 human malignant mesothelioma biopsies containing wild-type BAP1 and in 10 human mesothelioma biopsies containing mutated BAP1, as determined in previous studies." (PMID 30349006, 2018).
Myelodysplasia (1 paper, 2017). Clonal hematopoietic stem cell disorders characterized by dysplasia (ineffective production) in one or more hematopoietic cell lineages, leading to anemia and cytopenia. "Moreover, Asxl2-deficient mice exhibited hyposegmented neutrophils with hypogranular cytoplasm and circulating, multinucleated erythroid progenitors, which are features consistent with myelodysplasia." (PMID 28516957, 2017).
neuroblastoma (1 paper, 2021). Neuroblastoma (NB) is the most common solid, extracranial childhood tumor. "PI3Kα inhibitor PIK-75 (78.9% cytotoxicity) stimulates anti-neuroblastoma activity by destabilizing MYCN and sensitizing tumor cells to anthracyclines, and indeed increased cytotoxicity with PIK-75 was associated with PPM1D and GNA13 gain, and DNMT3A, CBL, EED and ASXL2 loss." (PMID 34722256, 2021).
Pancreatic Carcinoma (1 paper, 2021). "Our work helps to uncover the roles of ASXL2 in tumor immune microenvironment, the development of pancreatic cancer, and its potential value in therapeutic strategies determination." (PMID 34692512, 2021). "In conclusion, this is the first research to identify ASXL2 as a new potential prognostic biomarker in pancreatic cancer." (PMID 34692512, 2021). "To further validate the aberrant expression of ASXL2 in pancreatic cancer, we obtained additional gene expression data from GSE28735 and GSE62452." (PMID 34692512, 2021). "In the present study, we identified ASXL2 as a potential prognostic and predictive biomarker for pancreatic cancer." (PMID 34692512, 2021). "In summary, our results highlight that ASXL2 is a potential prognostic and predictive biomarker in pancreatic cancer." (PMID 34692512, 2021). "Although pancreatic cancer is one of the common malignancies, the role of ASXL2 in pancreatic cancer remains undefined." (PMID 34692512, 2021). "We extracted gene expression profiles from TCGA and Xena databases and noted that ASXL2 was highly expressed in pancreatic tumors." (PMID 34692512, 2021). "With a better understanding of its biological functions and regulatory mechanisms, ASXL2 may contribute to making biomarker therapies more effective for pancreatic cancer treatment in the future." (PMID 34692512, 2021). "This is the first research focusing on the prognostic value of ASXL2 in pancreatic cancer." (PMID 34692512, 2021). "Finally, the aberrant expression of ASXL2 in pancreatic cancer was validated by external datasets and biospecimens." (PMID 34692512, 2021). "Therefore, we investigated the effect of ASXL2 on the TIME in pancreatic cancer via several deconvolution algorithms." (PMID 34692512, 2021). "However, the role of ASXL2 in pancreatic cancer remains unclear." (PMID 34692512, 2021). "To figure out the potential role of ASXL2 in clinical treatment decisions, we estimated the IC50 of common drugs recommended for pancreatic cancer therapy by AJCC guidelines." (PMID 34692512, 2021).
Pancytopenia (1 paper, 2017). An abnormal reduction in numbers of all blood cell types (red blood cells, white blood cells, and platelets). "In the present study, we utilized an Asxl2 knockout mouse model to show that Asxl2 loss in mice leads to dysplastic haematopoiesis, pancytopenia and splenomegaly, resembling an MDS-like disease." (PMID 28593990, 2017). "Of note, a fraction of the recipient mice received Asxl2+/− or Asxl2−/− BM cells developed the MDS-like disease as evidenced by dysplastic features of myeloid lineages, pancytopenia and myeloid infiltration in the spleen and liver." (PMID 28593990, 2017).